EGFR (epidermal growth factor receptor)
Diseases named in the same sentence as EGFR in open-access papers (continued):
Sharing a sentence is not in itself a finding about the gene and the disease.
colon carcinoma (continued). "Ongoing studies are evaluating agents against the PI3K/mTOR route in combination with anti-EGFR antibodies in colon cancer." (PMID 26418718, 2015). "The epidermal growth factor receptor (EGFR) has been shown to be overexpressed in several solid tumors, especially in colon cancer (about 80% of patients), and has also been shown to mediate resistance to chemotherapeutic agents." (PMID 26491668, 2015). "We also confirm the synergistic activity of BRAF and EGFR inhibitors in BRAF-mutant colon cancer cell lines.The claim that EGFR and BRAF inhibitors are inactive in BRAF-mutant colon cancer lines appears unfounded however, as we observed a clear IC50 response." (PMID 26018524, 2015). "Together, these results demonstrate that the combination treatment of cetuximab and cisplatin suppressed colon cancer cell growth and induced apoptosis by EGFR downregulation via the ERK signaling pathway." (PMID 26491668, 2015). "Activating KRAS mutations in CRC tumor samples are an early event in the progression of colon carcinoma and the only predictive molecular marker useful for treatment decision as EGFR directed therapy is ineffective in the context of concomitant KRAS mutation." (PMID 24943349, 2014). "In Caco-2 cells (cell line obtained from human colon carcinoma), nitration of EGFR was first observed following the exposure to ONOO-." (PMID 25389386, 2014). "The discoveries which identified the ErbB2 receptor (HER2) and epidermal growth factor receptor (EGFR) as target cell surface molecules in breast and colon cancer, respectively, have led to development of effective therapies." (PMID 24465712, 2014). "Expression of a high level of EGFR has been found in various types of human cancers, including colon cancer, gastric cancer, lung cancer, breast cancer, and squamous cell carcinoma of head and neck." (PMID 24874286, 2014). "We have demonstrated for the first time that B4GALNT3 can regulate cancer stem cell properties via modifying EGFR glycosylation and signaling in colon cancer cells." (PMID 25003232, 2014). "These compounds prevent phosphorylation of EGFR induced by ionizing radiation and are potentially useful drugs for radio-sensitizing colon cancer cells." (PMID 25401399, 2014). "A recent study reported the emergence of MET amplification during anti-EGFR therapy eventually limited the efficacy of further treatment in colon cancer." (PMID 24714091, 2014). "Taken together, our results strongly indicate that PTPRO expression affects the sensitivity of colon cancer cells to EGFR inhibitors." (PMID 25301722, 2014). "It was demonstrated that CUR is able to inhibit EGFR and ErbB2 phosphorylation in breast and colon cancer cell lines and that the combined treatment of RES+CUR increases these effects in colon carcinoma cell lines." (PMID 25296980, 2014). "We found that suppression of CNDP2 blocked cell cycle progression and decreased the expression of cyclin E, cyclin B1 and EGFR in colon cancer cells." (PMID 24885395, 2014). "Rutin targets two proteins, namely NT5E and EGFR, which both interact with established colon cancer drug targets and two proteins that are part of the colon cancer prognostic signature gene set (CYP1B1 and ALOX5)." (PMID 24886433, 2014). "KRAS status is presently the only biomarker routinely used to select patients with colon cancer for EGFR inhibition-targeted therapy, which is widely used to treat metastatic colorectal cancer." (PMID 25297496, 2014). "EGFR hyperactivation is commonly observed in multiple types of epithelial cancers including colon cancer." (PMID 25301722, 2014). "In the present study, effects of concomitant inhibition of the epidermal growth factor receptor (EGFR) and DNA methyltransferase were examined in human colon cancer cells." (PMID 24874286, 2014). "Our results revealed that loss of PTPRO promotes resistance to EGFR inhibitors in colon cancer cells by maintaining activated SRC and EGFR/MAPK pathway." (PMID 25301722, 2014).
colon carcinoma (continued). "There is accumulating evidence that the biological synergy between SRC and EGFR promotes colon cancer tumorigenesis." (PMID 25301722, 2014). "For example, insulin-like growth factor-I receptor activation blocks doxorubicin cytotoxicity in sarcoma cells, and the EGFR inhibitor gefitinib sensitizes colon cancer cells to irinotecan." (PMID 24758355, 2014). "A sub group of colon cancer patients (~40%) harbor mutations in the KRAS oncogene, and are precluded from receiving anti-EGFR targeted therapies." (PMID 24798549, 2014). "As activation of EGFR is correlated with colon cancer progression, the EGFR has been the target of anticancer drug development efforts." (PMID 24874286, 2014). "Taken together, these data suggest B4GALNT3 regulates cancer stemness and the invasive properties of colon cancer cells through modifying EGFR glycosylation and signaling." (PMID 25003232, 2014). "We also found that B4GALNT3 plays an important role in regulating the colon cancer stem-like cell property by modulating the LacdiNAc structure on EGFR." (PMID 25003232, 2014). "In the present study, we have investigated the differences in the expression patterns of CD133, CD24, CD44 and EGFR in three colon cancer cell-lines; HT-29, HCT116 and DLD-1." (PMID 24760019, 2014). "Here we found that up-regulation of SRC activity by loss of PTPRO dramatically affects activation of EGFR/MAPK pathway, further confirming the contribution of the SRC kinase to colon cancer development and progression." (PMID 25301722, 2014). "There have been multiple investigations of chemotherapeutics that target EGFR and thereby attenuating the EGFR signaling pathway in colon cancer." (PMID 24874286, 2014). "We propose that the cPLA2α is a potential therapeutic target for treatment of colon cancer that are resistant to anti-EGFR therapy in the results of constitutive activation of AKT." (PMID 25365190, 2014). "In this study, we first showed that B4GALNT3 modulates the LacdiNAc on EGFR, influences its activity and signaling in colon cancer cells, and in turn alters cancer stemness property." (PMID 25003232, 2014). "A similar mechanism, with the participation of MMPs, has been shown in colon carcinoma cells where PAR1-mediated enhanced cell proliferation is stimulated by an MMP-dependent transactivation of the EGFR." (PMID 24215724, 2013). "We reported that berberine significantly inhibited basal level and EGF-stimulated EGFR activation and proliferation in the immorto Min mouse colonic epithelial (IMCE) cells carrying the APCmin mutation and human colonic carcinoma cell line, HT-29 cells." (PMID 23457600, 2013). "The activation of TGFα-EGFR signaling in primary colon tumors contributes to the spread of tumor cells to lymph nodes and the liver." (PMID 23986907, 2013). "Our in vitro data indicate that berberine plays an anti-proliferative role and down-regulates EGFR in colon tumor cells." (PMID 23457600, 2013). "The aim of this study was to investigate the effects and mechanisms of berberine on regulation of EGFR and proliferation in colon tumor cells." (PMID 23457600, 2013). "Since we have reported that berberine stimulates ROS production in colon tumor cells to stimulate caspase-independent cell death, we have tested the role of ROS scavenger on berberine regulation of EGFR and proliferation." (PMID 23457600, 2013). "The epidermal growth factor receptor (EGFR) cascade was upregulated in colon cancer, but administration of ginseng significantly reduced EGFR activation." (PMID 24288570, 2013). "Both studies applied the combined treatment for inhibiting COX-2 and ERBB2, and COX-2 and EGFR to exert the anti-angiogeneic effect on colon cancer cell lines and xenograft models." (PMID 23967306, 2013). "The aim of this study was to investigate the effects and mechanisms of berberine on regulation of EGFR activity and proliferation in colonic tumor cell lines and in vivo." (PMID 23457600, 2013).
colon carcinoma (continued). "Colon cancer cells secrete TGFα in response to hypoxia and the ligand signals, the cell surface EGFR, to initiate a sequence of cell survival programs." (PMID 23986907, 2013). "We provided a plausible mechanism of berberine's action, which involves stimulation of Cbl activation, thus enhancing EGFR down-regulation, leading to inhibition of proliferation in colon tumor cells." (PMID 23457600, 2013). "The authors demonstrated that the reduction of EGR-1 activity plays a critical role in the inhibition of EGFR expression in human colon cancer cells." (PMID 23251236, 2013). "To further study the role of Cbl activation in berberine-induced down-regulation of EGFR and inhibition of proliferation in colon tumor cells, we knocked down Cbl expression in IMCE cells by transfecting Cbl targeted siRNA." (PMID 23457600, 2013). "Cbl is required for berbrine down-regulation of EGFR and inhibition of proliferation in colon tumor cells." (PMID 23457600, 2013). "The decision to incorporate EGFR antibodies in a colon cancer chemotherapeutic regimen also involves the choice between using cetuximab or panitumumab." (PMID 24276379, 2013). "N-terminal fragments of EGFR ligands including heparin-binding epidermal growth factor like growth factor (HB-EGF) which is considered to be involved in mainly cell proliferation in colon cancer cells bind to EGFR and induce its phosphorylation." (PMID 23451083, 2013). "We previously reported that the simultaneous blocking of two RTK pathways, i.e., the insulin-like growth factor receptor (IGF-IR) and EGFR pathways, produced more efficient therapeutic effects in colon cancer cell lines than the inhibition of a single pathway." (PMID 23900414, 2013). "Previously, in human colon cancer cells, we showed that cholinergic agonists stimulate cell proliferation by trans-activating EGFR and stimulate post-EGFR signaling." (PMID 23617763, 2013). "Taken together, these data indicate that berberine enhances Cbl activity, resulting in down-regulation of EGFR expression and inhibition of proliferation in colon tumor cells." (PMID 23457600, 2013). "TGFα-EGFR signaling in colon cancer cells creates a microenvironment that is conducive for metastasis, providing a rationale for efforts to inhibit EGFR signaling in TGFα-positive cancers." (PMID 23986907, 2013). "One mechanism explaining this difference is the feedback activation of EGFR upon treatment with vemurafenib and the fact that EGFR levels are higher in colon cancer than in melamoma cells." (PMID 23587292, 2013). "Recent studies have shown that NSAID's can be beneficial as they can induce cell death and inhibit epidermal growth factor receptor signalling via the MAPK pathway in colon cancer." (PMID 23840550, 2013). "A mechanistic study showed that TNC promotes colon carcinoma cell invasion via the epidermal growth factor receptor (EGFR) and hepatocyte growth factor (HGF) signaling pathways; TNC secreted by CAFs activates EGFR and HGF." (PMID 22481923, 2012). "We conclude that DHA-induced alteration in both the lateral and subcellular localization of EGFR culminates in the suppression of EGFR downstream signal transduction, which has implications for the molecular basis of colon cancer prevention by DHA." (PMID 22761867, 2012). "Signaling through EGFR is up-regulated in colon cancer, and inhibition of signaling through EGFR has been shown to prevent colon tumor formation." (PMID 22761867, 2012). "It was reported that Cld2 expressed in colon cancer cells promoted EGFR-mediated proliferation in vitro, and we reported that Cld4 in the thymocytes was capable of enhancing the TCR-mediated ERK activation." (PMID 23284964, 2012). "We previously revealed a requirement of cancer cells for NEU3 in vitro: the siRNA-mediated knock down of NEU3 induces the apoptosis of human cancer cells including colon cancer cell lines accompanied by suppression of the EGFR signaling pathway." (PMID 22815940, 2012).
colon carcinoma (continued). "They showed that a feedback activation of EGFR occurs in colon cancer cells after BRAF-V600E inhibition very quickly." (PMID 23056577, 2012). "Findings described in the present study reveal a novel mechanism whereby FXR regulates cell proliferation through EGFR signaling in colon cancer cells." (PMID 23119029, 2012). "In fact, this feedback activation of EGFR in colon cancer cells leads to a continuous malignant cell proliferation even in the presence of BRAF-V600E inhibition." (PMID 23056577, 2012). "In the present study, we have found that neurotensin-induced signalling in colon carcinoma cells involves both EGFR-dependent and -independent pathways." (PMID 21961726, 2011). "Colonic tumors induced by AOM/DSS in mice on Western diet showed up-regulations of phospho-active-EGFR (pEGFR), pErbB2, pERK, and pAKT." (PMID 22070864, 2011). "The EGFR cascade was up-regulated in colonic tumors and ginseng significantly reduced EGFR and ErbB2 activation and Cox-2 expression." (PMID 22070864, 2011). "Collectively, these findings define efficacious bile acid concentrations, emphasize the importance of co-expression of CHRM3 and EGFR for bile acid-induced colon cancer cell proliferation, and identify the key role of post-EGFR ERK signaling." (PMID 24212649, 2011). "The expression of the EGFR was generally up-regulated in colon cancer patients in this study, which is coherent with earlier published studies." (PMID 22194989, 2011). "The treatment of colon cancer cells with nicotine activated c-Src as well as augmented EGFR expression." (PMID 22085699, 2011). "Bile acids protect colon cancer cells from apoptosis by EGFR-, PI3K/AKT-dependent mechanisms that involve activation of NF-κB." (PMID 24212649, 2011). "Ectopic express HDAC3 induceda greater magnitude of EGFR mRNA and a positive correlation between EGFR and HDAC3expression in colon cancer patients." (PMID 21464950, 2011). "On the other hand, EGFR signaling also induces colon cancer cell proliferation, survival, and migration/invasion through multiple pathways in a PTGS2 (COX-2)-independent manner." (PMID 24213116, 2011). "In human colon cancer EGF receptor (EGFR) expression and activity are increased, and targeting this receptor has played an increasing therapeutic role." (PMID 21639915, 2011). "Next, we wanted to clarify if the levels of IFNα/βR1 and EGFR correlated with the CysLT2R pattern in a colon cancer patient array." (PMID 22194989, 2011). "Using in vitro and xenograft assays, it was also reported that the levels of Src and EGFR in colon cancer cells were significantly increased following nicotine exposure." (PMID 22085699, 2011). "The expression pattern for CysLT2R is similar to the expression of anti-tumorigenic IFNα/βR1while the expression of CysLT1R is increased in colon cancer similar to the expression of EGFR." (PMID 22194989, 2011). "We found that 214 of 361 (59%) colon carcinomas examined showed EGFR plasma membrane staining (1–3+)." (PMID 19997103, 2010). "In this study, we use epidermal growth factor (EGF), a key trigger in activating the EGFR signaling pathway, to stimulate caco-2 colon carcinoma cells which were tested to overexpress EGFR." (PMID 23554613, 2010). "Nevertheless, up till now there is a substantial lack of prospective clinical trials, reporting data on QoL during anti-EGFR therapy in colon cancer patients." (PMID 20398332, 2010). "Colon cancers with strong EGFR (3+) vs other intensities (0–2+) were significantly more likely to be stage III (87 vs 73%; P=0.03)." (PMID 19997103, 2010). "This monocentric cross sectional study is carried out to assess quality of life in colon cancer patients experienced skin side effects due to anti epidermal growth factor receptor inhibitors therapy." (PMID 20398332, 2010). "The recent incongruity observed among EGFR-expressing colon cancer patients and responsiveness to cetuximab is a case in point." (PMID 20346177, 2010).
colon carcinoma (continued). "Elongation of this repeat was shown to result in the downregulation of EGFR mRNA levels in human colon cancer cells and in human tumours with MSI." (PMID 19997103, 2010). "This study documents the impact of skin side effects on quality of life of advanced colon cancer patients treated with EGFR inhibitors." (PMID 20398332, 2010). "Anti-EGFR therapies have been shown to inhibit EGFR phosphorylation and to reduce proliferation in human colon cancer cells and in tumour xenografts." (PMID 19997103, 2010). "Epidermal growth factor receptor inhibitors' skin side effects have an important impact on quality of life in advanced colon cancer patients; symptoms scale is the most effect respect to emotional and functioning scales." (PMID 20398332, 2010). "The National Comprehensive Cancer Network (NCCN) now recommends KRAS testing prior to initiation of anti-EGFR therapy in colon cancer patients." (PMID 21110880, 2010). "Such issues are highly relevant to locoregionally advanced colon cancers, as anti-EGFR antibodies are currently being studied in the adjuvant setting in this patient population." (PMID 19997103, 2010). "In contrast to phospho-EGFR, EGFR expression in primary colon cancers has been shown to be an adverse prognostic marker in some, but not other, studies and an evaluation of its prognostic effect using the FDA-approved antibody and methodology is lacking." (PMID 19997103, 2010). "Phospho-EGFR expression was detected in 157 of 388 (40%) colon cancers using an antibody that recognises the major EGFR autophosphorylation site at Tyr-1173." (PMID 19997103, 2010). "EGFR is abnormally activated in many epithelial tumors and is frequently overexpressed in colon cancer correlating with poor response to treatment, disease progression, and poor survival." (PMID 18691415, 2008). "To better study the possible responses after stimulation with EGF and the anti EGFR molecules cetuximab and gefitinib, we began by characterizing the two human colon cancer cell lines utilized (HT-29 and Caco-2) as working models." (PMID 18691415, 2008). "We, and others, have previously shown that colon tumours that acquire resistance to anti-EGFR drugs cetuximab and gefitinib overexpress Akt and VEGF, which act as the escape pathways to overcome the EGFR blockade." (PMID 18319715, 2008). "Out of the four members of the type I receptor tyrosine kinase family, EGFR and Her-2 have been widely studied on several human tumors, mostly breast and colon carcinoma." (PMID 16507107, 2006). "Some of them are previously known translational controlled genes such as EGFR, one of the key targets for the latest targeted anticancer drug development for colon cancer treatment." (PMID 16584549, 2006). "We now report, for the first time, that sulindac metabolites inhibit EGFR phosphorylation and downregulate the expression of total EGFR protein in human colon cancer cells." (PMID 16138927, 2005). "Treatment with EGFR AS oligonucleotides showed an inhibition of human colon cancer cell growth with potentiation of inhibitory cell growth effects in combination with cytotoxic drugs." (PMID 14520471, 2003). "Emerging evidence suggests that ANXA1 may contribute to immune suppression within TME via its functional interaction with the EGFR pathway, a key regulator of cell proliferation and tumor progression in both colon cancer and RC." (PMID 41283264, 2025). "A lack of response to BRAF inhibitors could also be due to overexpression of resistance pathways, notably EGFR as is seen in colon cancer." (PMID 40869231, 2025). "Although the EGFR pathway is considered unresponsive to treatment in patients with KRAS mutations, recent research in 2025 found that EGFR still plays an active role in colon cancer cells with KRASG12D mutations." (PMID 41226554, 2025).